LAMP1 (lysosome associated membrane protein 1)
Diseases named in the same sentence as LAMP1 in open-access papers (continued):
Sharing a sentence is not in itself a finding about the gene and the disease.
infection (continued). "Infection with live Mav will over time yield a mixture of live and dead bacteria residing in different subcellular compartments, whereas dead Mav should all be routed to LAMP1+ phagolysosomes for degradation." (PMID 28806745, 2017). "Therefore, we tried to determine the localization of CathepsinD and Lamp1 on Leishmania-PV after 24 h of infection in human macrophages." (PMID 28650977, 2017). "We found that both LAMP1 and pLyn were colocalized with internalized Pa at 8 h post infection." (PMID 26735693, 2016). "Therefore, regulation of CTSS at 4 h post infection is consistent with the co-localization of LAMP1 signals as a late marker of phagolysosomal processing." (PMID 27014637, 2016). "Conversely, infection by ΔdotA mutant L. pneumophila, which lack a functional Dot/Icm secretion system, resulted in minimal levels of anti-Calnexin staining (~2%) and substantial anti-LAMP1 colocalization (~74%)." (PMID 27459495, 2016). "Co-localization of Salmonella with the lysosome-associated membrane protein 1 (LAMP-1), clearly indicated that I-switch-incorporated Salmonella were in the SCV within 30 min after infection in macrophages and remained so during 6 h of macrophage infection." (PMID 25875623, 2015). "In our in vitro cell culture infection system, we also found that UCVs are LAMP1 positive." (PMID 26248231, 2015). "By 9–12 days after infection, all detected bacteria were surrounded by Lamp-1." (PMID 24586722, 2014). "While we could demonstrate that pUL78 was localized to lysosomes early in infection in HFFs, the dot-like signals of pUL78, located close to the nucleus, showed clear colocalization with LAMP-1 in ARPE-19 cells starting at 72 h post infection." (PMID 24517969, 2014). "Upon infection of corneal cells, significantly more viral DNA was present in the fraction 10, containing caveolin-1and pSrc, than in fraction 6, which was abundant in LAMP1 (fraction 6 vs. fraction 10 in virus infected cells: p=.0027)." (PMID 24147000, 2013). "In cells depleted of Tsg101, Hrs, or Rab7, we observed diminished co-localization between Mtb and LAMP1 and a concomitant increase in co-localization of Mtb with TfR compared to control cells 24 hours post-infection (hpi), suggesting decreased Mtb delivery to degradative compartments." (PMID 24204276, 2013). "Interestingly, O'Leary and collaborators have demonstrated that IL-10 production by immune cells can affect the ability of M. tuberculosis to escape the LAMP1+ late endosomal compartment and to establish infection in human macrophages in vitro." (PMID 23818855, 2013). "In addition at 3 hours post-infection the bacteria were often found co-localized with the late lysosome marker LAMP1." (PMID 23284947, 2012). "Thus, confocal microscopy was used to determine the percentage of LAMP-1 colocalization for ΔvgrG or ΔdotU mutant bacteria expressing Green fluorescent protein (GFP) 3 h post infection in J774 macrophages." (PMID 22514651, 2012). "In macrophages fixed after 48 h of infection, the immunostaining for the PV membrane components LAMP1 and LAMP2 indicates that L. major PVs containing two or three amastigotes (some of them undergoing binary division) may be observed." (PMID 22348167, 2012). "The amount of LAMP-1 and LAMP-2 associated with E. coli phagosomes increased at each time-point over the first two hours, from a low immediately after infection to a high that was maintained between two and four hours after infection (ECOL)." (PMID 21426584, 2011). "At day 6 post-infection, more than 80% of organisms co-localized with both cathepsin D and Lamp-1." (PMID 21179488, 2010). "Whereas, in wild-type macrophages, greater than 60% of the phagosomes containing the pathogen co-localized with LAMP-1 within 30 min post-infection, less than 30% of the L. pneumophila containing vacuoles in caspase-7−/−, caspase-1−/− and A/J-derived macrophages acquired LAMP-1." (PMID 19343209, 2009).
infection (continued). "After 4 h of infection of intestine 407 cells, bacteria replicated in the cell cytoplasm and were enclosed in membrane-bound vesicles positive for the late endosomal marker, LAMP1." (PMID 19709415, 2009). "Confocal microscopy, transmission electron microscopy, and anti-LAMP1 antibody labeling studies showed that conidia of both species were phagocytosed and trafficked into a late endosomal-lysosomal compartment as early as 4 h post-infection." (PMID 18564423, 2008). "Moreover, although the CTSB puncta (red) increased after infection, the LAMP1-CTSB colocalization (yellow puncta) was significantly reduced in infected cells, compared with high colocalization in control cells, indicating that most of elevated cytosolic CTSB is extra-lysosomal at 12 hpi." (PMID 41277866, 2026). "Furthermore, it is interesting to note that the functional analysis of MFA clusters 1 and 2 (only 1° infection) reveals a role in vesicle-mediated transport and supports our LAMP1 data showing more LAMP1-positive lysosomal compartments detected in the 1° infection." (PMID 38956024, 2024). "We found that ∼11% of intracellular L. monocytogenes cells remained trapped in LAMP-1-positive vacuoles 2 h post-infection, which increased to 20% in stimulated HBCs, consistent with the notion that HBCs may successfully kill a small proportion of phagosomal L. monocytogenes." (PMID 34399615, 2021). "However, leptospires partially colocalize with the lysosomal marker LAMP-1 after infection." (PMID 33123147, 2020). "Fluorescence microscopy further demonstrated that during the course of infection, Y. pseudotuberculosis-containing vacuoles (YCVs) enlarge progressively overtime by fusing with LC3-positive membranes, and harbor the lysosomal associated membrane protein 1 (LAMP1)." (PMID 33291818, 2020). "However, it remains to be determined whether Ngo can accelerate CD46-cyt1 and LAMP1 degradation at high MOI condition used in HeLa cell infection." (PMID 30753248, 2019). "However, despite the robust Ply-driven autophagic targeting of SPN, most of Gal8 positive PCVs, showing association with LC3 and LAMP1, failed to accumulate LysoTracker till delayed hours post infection." (PMID 30011336, 2018). "LAMP1 may also promote infection by positioning LASV particles in proximity to the target membrane." (PMID 30265711, 2018). "Within 30–60 min post infection (p.i.), early SCV matures into late SCV by loss of early endosomal proteins and simultaneous acquisition of selective late endosomal and lysosomal proteins including Rab7, lysosomal glycoproteins (lgps) such as, LAMP1 and LAMP2 and v-ATPases." (PMID 29084291, 2017). "In addition, EmGFP-Rab30 clearly overlapped with LAMP1-positive GcAV at 4 h after infection." (PMID 26771875, 2016). "In cells infected with the sifA strain, LAMP1-GFP-positive membranes were found in the vicinity of the bacteria in the early phase of infection (4-5 h p.i.)but at later time points (≥ 8 h p.i.), an association between the intracellular bacteria and LAMP1-postive compartments was usually absent." (PMID 25522146, 2014). "LAMP-1 was also more rapidly associated with autophagosomes harboring 188NADase- compared to parent strain 188, although less so than the SLO-mutant: 27% of autophagosomes containing 188NADase- were positive for LAMP-1 at 1 h post-infection, 64% at 3 h, and 82% at 6 h." (PMID 23762025, 2013). "These PVs increased in size (reaching diameters of the order of 10 μm) and maintained the LAMP1-positive phenotype, with apparently higher concentrations of this lysosome marker in the contact sites between PV membranes and parasite posterior poles (48 h post-infection)." (PMID 22348167, 2012). "Moreover, the amount of LAMP-1 exposed at the cell surface increased at longer times of infection." (PMID 22848580, 2012).
infection (continued). "On one path, ubiquitinated bacteria are sequestered into LAMP-1 positive compartments; this may limit spread of infection and lead to direct toxicity to the enclosed bacteria; on the other path, bacteria shed cell wall material and possibly escape ubiquitination and sequestration." (PMID 19436699, 2009). "Interestingly, while the percentage of conidia in Lamp1+ vesicles increased over the infection period, the percentage of Lamp1+Actin+ vesicles plateaued after one hour, suggesting that actin recruitment to phagolysosomes may be limited to specific stages of vesicle maturation." (PMID 40066070, 2025). "The results showed that at all post-infection time points, most LC3-positive MCVs were also positive for LAMP1." (PMID 39746091, 2025). "Infection with C. albicans has been reported to induce increased expression of autophagy markers LC3, ATG5, and LAMP1, and study also showed that apoptosis and necrosis was reduced in human vaginal epithelial cells overexpressed with wild-type ATG5." (PMID 40727105, 2025). "To validate the functional roles of key DEGs, we performed in vivo knockdown experiments for PPO2, RAB11B, LAMP1, and Dorsal during DIV1 infection, and double-stranded green fluorescent protein (dsGFP) was used as a control (each 30 individuals)." (PMID 40679295, 2025). "Early in infection, we observed some differences in the trafficking of EBOV GP—lower and enhanced GP colocalization with lysosomal marker LAMP1 was seen in GALNT2 KO and GALNT3 KO cells, respectively." (PMID 38757972, 2024). "For this, HeLa cells expressing LAMP1-HaloTag were infected with STM, at 8 h post infection the cells were stained with 100 nM JFX554 and prepared for in-resin CLEM." (PMID 38560224, 2024). "To address this question, we measured LAMP1 at the cell surface and, in parallel, the number of Salmonellas secreted by HEK293A and HEK293Cx43+ after infection by measuring the number of colony forming units (CFUs) in the intra- and extracellular fraction." (PMID 39044100, 2024). "Second, the mRNA levels of LAMP1, cathepsin D, and LC3 all behaved distinctly depending on infection, time, and genotype." (PMID 38051049, 2024). "The percentage of LAMP-1-positive GAS was 60.9% and 16.2% of Cap(+) and Cap(–) strains, respectively, after 4 h of infection." (PMID 38819157, 2024). "Overall, these findings demonstrated that the sialidase activity of the HN protein is crucial for the deglycosylation and degradation of LAMP1 and LAMP2, ultimately leading to cellular LMP and apoptosis during the infection of diverse NDV strains." (PMID 38354122, 2024). "Expression of several transmembrane molecules such as LAMP-1 (human), ATPase, and TSPAN8 transmembrane proteins was significantly upregulated in CRFK cell-derived EVs’ post-infection." (PMID 39091390, 2024). "Interestingly, when we examined whether the LAMP1+ compartment harboring the relatively small population of ΔhlyD, harbored in this compartment, became acidic following infection with BECs, the majority of vesicles took up the acidotropic dye (white arrowheads, and 4F)." (PMID 37167325, 2023). "Surprisingly, at the very early stages of infection (1 DPI), we detected a significant increase in the levels of active Rab7 and in its colocalization with Lamp1 in 22L-infected CGN cultures compared with the mock-infected control CGNs." (PMID 36623732, 2023). "At 72 hours after infection with C. burnetii, a large CCV that contained the lysosomal marker Lamp1 was observed in the host cells in fluorescence confocal analysis." (PMID 38282619, 2023). "Here, we show the progression of the colocalisation of DRAM1 with Mm over the course of infection, and study this in relation to LC3, LysoTracker and LAMP1 patterns, as markers for autophagosomes and (endo)lysosomes." (PMID 36980169, 2023). "In the cells expressing CP204L after transfection or after infection, VPS39 aggregates were largely separated from LAMP1-marked lysosomes, which concentrated in the area near the nucleus." (PMID 36722971, 2023).
infection (continued). "At the later stages of infection, concomitant with the increase in PrPSc levels (5 DPI), a reduction of active Rab7 and its colocalization with Lamp1 was observed, consistent with our findings in the neuronal cell lines persistently infected with 22L prions." (PMID 36623732, 2023). "As infection proceeded, SERINC5 translocated sequentially to early endosome (EEA1), late endosome (Rab7) and lysosome (LAMP1)." (PMID 36223419, 2022). "At 2 h after infection with the wt strain, the colocalization of the FCP with the early endosomal marker EEA1 was only 5.4% and with LAMP-1 8.51%, indicating that the majority of F. novicida were either in the cytosol or in a compartment lacking these markers." (PMID 35077486, 2022). "A549 and DF-1 cells transduced with LAMP1-WT, LAMP1-d384 or an empty vector were inoculated with LCMV-LASV GPC, and infection was quantified by microscopy after immunostaining for the LCMV NP protein." (PMID 35969633, 2022). "Secondly, the activation of trafficking regulators LAMP1, LAMP2, and lysosomal enzyme GLA at the transcriptional level activated immune responses, weakening the B. abortus growth at 4 h post-infection (pi)." (PMID 35631117, 2022). "Unlike macrophages, roughly 30% of A. fumigatus spores are internalized by lung epithelial cell line A549, and roughly half the internalized conidia colocalize with endosomal markers LAMP1 and CD63 after 24 h of infection." (PMID 34983375, 2022). "At 16 hr post-infection, cells were fixed with PFA and immuno-stained with anti-LAMP1 and anti-HA antibodies to reveal the SIFs and secreted SseJ." (PMID 34061032, 2021). "At 16 hr post-infection, cells were fixed with paraformaldehyde (PFA) and immuno-stained with anti-LAMP1 antibody to reveal the SIFs." (PMID 34061032, 2021). "Compared with infection with FITC-labeled Mtb alone, treatment with IMQ enhanced the overlapping signal of FITC-labeled Mtb with LC3 and LAMP-1, as well as LAMP-1 accumulation." (PMID 32765474, 2020). "As early as 3 h post-infection, 27% of the late endosome marker Rab7 (PCC: 0.268), 22% of the late endosome/lysosome LAMP1 (PCC: 0.2158), and the 35.5% of the class II MHC molecules (PCC: 0.3551) colocalized partially with the BcCVs." (PMID 32873215, 2020). "GFP-LVS-infected macrophages in the presence of naïve or LVS-immune lymphocytes 48 h after infection were stained with markers of the endosomal (EEA1 and LAMP1), lysosomal (Cathepsin D and Lysotracker), and autophagic pathways (LC3B)." (PMID 32694562, 2020). "We focused on mouse macrophages between 24 and 74 h after infection, using confocal microscopy coupled with staining for markers for the endosomal (EEA1 and LAMP1), autophagic (LC3B), and lysosomal (Cathepsin D and Lysotracker) pathways." (PMID 32694562, 2020). "After infection, ΔiglE mutants localized within the LAMP‐1‐positive area, whereas the wild‐type and complemented strains grew in areas distant from the LAMP‐1‐positive area." (PMID 29978561, 2019). "Coupling these three prior observations with our finding that LASV GPC-mediated entry and infection can occur (albeit at reduced efficiency) in Lamp1 KO cells, we postulated that by binding to LASV GPC, Lamp1 promotes fusion at a higher (less acidic) pH." (PMID 29295909, 2018). "Detailed studies of the role of LAMP1 revealed that in the acidic LE/LY, LASV GP dissociates from α-DG and binds to LAMP1, which markedly enhances virus membrane fusion and infection." (PMID 30265711, 2018). "We propose that by promoting fusion and entry in less acidic endosomes, Lamp1 increases the overall efficiency of LASV entry and infection." (PMID 29295909, 2018). "Since infection in Lamp1 KO cells is ~20% that seen in WT cells, we used two inputs (low and high) of titer-determined LASV MLV pseudoviruses to achieve a roughly equivalent infection signal in WT (low input) and Lamp1 KO (high input) cells." (PMID 29295909, 2018).
infection (continued). "Taken together, we propose that Lamp1 increases the overall efficiency of LASV entry and infection by promoting fusion in a more hospitable, less acidic endosomal compartment." (PMID 29295909, 2018). "While LAMP-1 displays a dispersed pattern throughout the cytoplasm in uninfected cells, cells infected with HSV (12–24 h post-infection) show the LAMP-1 marker concentrated in MVBs and late endosomes." (PMID 30386309, 2018). "Lysosomal proteins LAMP-1 and 2 have been shown before to interfere with parasite invasion, since LAMP1/2 knock out cells led to very low levels of cell infection." (PMID 28586379, 2017). "Our results suggest that upon infection of WT DCs with B. abortus, TLR7 traffics to LAMP-1+ endosomes, spreading throughout the cells." (PMID 28167945, 2017). "Synchronized infection experiments were performed and LAMP1 signal (as a late phagosomal marker) was studied on viable and heat killed (HK) BCG containing phagosomes for up to 4 h post infection." (PMID 27014637, 2016). "There was a gradual increase in the levels of H. pylori-induced EEA-1 and LAMP-1 expression, and a concurrent increase in the conversion of LC3-I to LC3-II, over the course of the infection." (PMID 28144585, 2016). "To determine which autophagy proteins mediate BTZ resistance, we rescued LAMP-1, Beclin 1, and LC3B expression in ARP-1 cells by infection with lentivirus containing human LAMP1, Beclin-1, or LC3B ORFs, respectively." (PMID 25895124, 2015). "Consistent with this, at 4 h post-infection, the bacteria inside ESDM were predominately co-localized with Lamp-1, as revealed by double staining." (PMID 25752829, 2015). "After infection with Salmonella, WIPI2 on p62-positive SCVs colocalized with LC3, LAMP1, and ubiquitin." (PMID 24954904, 2014). "Adult Drosophila females, carrying transgenic Rab7-GFP endosome and Lamp1-GFP lysosome markers, were injected with E. coli DH5α and the hemocytes were collected at 15, 30, 45 and 60 minutes after infection." (PMID 24709696, 2013). "Membranous organelles were examined and no major alterations of the ER, Golgi complex and lysosomes were found at day 10 post-infection based on the immunofluorescent analysis of protein disulfide isomerase (PDI), giantin, and LAMP1, respectively." (PMID 24098492, 2013). "ASFV virions stained with an antibody against major capsid protein p72 colocalized at high percentages with EEs within the first 30 min of infection, while colocalization with CD63, Rab7 and Lamp1 was very low at this time point." (PMID 23133661, 2012). "By 1 h of infection, the distribution of amastigotes in LAMP-1-negative and LAMP-1+ compartments was 19% and 81%, respectively." (PMID 21552562, 2011). "The amount of LAMP-1 and LAMP-2 co-localised with phagosomes steadily increased at the 15 minute, 30 minute and two hour time-points post-infection, and reached a maximum between two and four hours after infection." (PMID 21426584, 2011). "As a consequence of infection, LC3, LAMP1 and MHC class II molecules are retained within the H. pylori-containing vacuoles and export of MHC class II molecules to cell surface is blocked." (PMID 20523725, 2010). "Infection with Nef-expressing HIV resulted in the lossof cell surface MHC-I and an increase in intracellular MHC-I, some of whichco-localized with LAMP-1 (compare rows 1 and 3)." (PMID 18725938, 2008). "Large LAMP-1 positive CCVs were only present at day 4 post-infection, but not at day 1 post-infection." (PMID 40586810, 2025). "Moreover, knockdown of PPO2, RAB11B, LAMP1, and Dorsal resulted in more severe hepatopancreatic damage post-DIV1 infection compared to the control group." (PMID 40679295, 2025). "MK-8722 treatment during infection significantly restored LAMP1 relative expression to its level in non-infected non-treated condition (1.15 ± 0.11 fold change, ANOVA: P < 0.01 compared to infected non-treated condition)." (PMID 40503889, 2025).